EGFR (epidermal growth factor receptor)
Diseases named in the same sentence as EGFR in open-access papers (continued):
Sharing a sentence is not in itself a finding about the gene and the disease.
tumor (continued). "ZD6474 displays antitumour efficacy by directly inhibiting tumour cell proliferation and survival via EGFR and RET inhibition, as well as tumour angiogenesis via VEGFR inhibition." (PMID 17912240, 2007). "Many clinical parameters which have been shown to correlate with response to EGFR TKIs, including smoking history, gender, ethnicity, and tumor histology." (PMID 17096850, 2006). "In the present study, EGFR immunostaining in the tumour was found to be a useful factor for making decisions to use targeted chemoradiotherapy." (PMID 16670721, 2006). "This ability to reduce tumour neoangiogenesis by EGFR targeting has been attributed to the inhibition of proangiogenic tumour factors such as VEGF and FGF." (PMID 16940984, 2006). "The aberrant activation of the EGFR leads to enhanced proliferation and other tumour-promoting activities, which provide a strong rationale to target this receptor." (PMID 16722544, 2006). "An interesting recent study points out that EGFR targeting of tumours can also include the endothelial cell network." (PMID 16940984, 2006). "Somatostatin receptor (SSTR) expression is positively correlated with tumor size and inversely correlated with epidermal growth factor receptor (ErbB) levels and tumor differentiation." (PMID 16519802, 2006). "GLM-1R tumour xenografts in nude mice exhibited more differentiated histology with well-defined tubular structures and stronger membranous staining of EGFR than parental GLM-1 tumour, whereas HER2 expression remained unchanged between the two." (PMID 17088902, 2006). "Cell lines were chosen as tumor surrogates for ease of handling, the ability to assay EGFR and downstream signalling events by biochemical methods, and the capacity to test inhibitors in a controlled environment." (PMID 17096850, 2006). "This is a very high percentage compared with previous studies in which the EGFR gene status was clarified in about 30% of patients using biopsy or resected tumour specimens." (PMID 17047654, 2006). "We also sequenced exons 18–23 of the EGFR gene of tumours in 20 patients with NSCLC who had been treated with gefitinib, and nine tumours had the mutations." (PMID 16552419, 2006). "We found that the residual tumour xenograft in nude mice 1–2 month after gefitinib treatment also showed upregulation of EGFR." (PMID 17088902, 2006). "Representative primary and recurrent tumor sections were stained using mouse anti-EGFR antibodies and only membranous staining of malignant cells was recorded." (PMID 17163999, 2006). "ZD6126 directly affects the internal structure of the endothelial cell, whereas gefitinib acts through inhibition of EGFR signalling of endothelial cells and by reduced production of proangiogenic factors by tumour cells." (PMID 16940984, 2006). "Several in vitro studies have shown that tumor cells which are sensitive to EGFR-targeted therapy, will also respond to the inhibitory effects of a number of cytotoxic drugs, which differ in their mechanism of action." (PMID 17163999, 2006). "This analysis of paired skin and tumour tissue clearly supports our results and questions the utility of skin rash as an optimal surrogate outcome marker for EGFR-directed therapies." (PMID 16306877, 2006). "Robust predictive markers are needed in order to identify the relatively small subsets of patients whose tumours are likely to respond to EGFR-targeted therapies." (PMID 16622439, 2006). "We concluded that InsR-A reduces sensitivity to gefitinib in LoVo CRC cells, thus its co-targeting alongside EGFR can improve the anti-tumour effect of gefitinib." (PMID 16819546, 2006). "In sum, the model which emerges is one in which STAT3 signalling downstream from EGFR is required for persistent cell motility and invasion, and that partial abrogation of this pathway hinders this tumour progression." (PMID 16804520, 2006).
tumor (continued). "The ability to predict the activity of an EGFR inhibitor on individual patients, or groups of patients based on the examination of molecular fingerprints from tumour specimens holds a lot of promise to move this investigational field forward." (PMID 16570047, 2006). "High levels of EGFR was also found in the nuclei of many tumours, including those of skin, breast, bladder, cervix, adrenocorticord, thyroid and oral cavity." (PMID 16434982, 2006). "If tumour cells are able to switch the main growth pathway from the her2/neu receptor to the EGFR or other signal transduction pathways, a continued treatment would not necessarily lead to a benefit." (PMID 16539726, 2006). "Herein, we report that STAT3 signalling downstream from EGFR autocrine activation leads to increase tumour cell motility and invasiveness." (PMID 16804520, 2006). "Previous studies found that nearly 50% of patients with advanced stage IV NSCLC who had previously received cytotoxic chemotherapy had clinical benefit with EGFR TKI defined as either overt tumor response (shrinkage) or stable disease." (PMID 17096850, 2006). "We not only found the effect of gefitinib on the EGFR-overexpressing cancer cells, but also found it on tumour vessels of the xenograft of ACT-1 cells." (PMID 15785737, 2005). "When a stably transfected cell instead of transient system was examined for drug sensitivity, however, it not only showed a significant increase in EGFR expression, but also enhanced survival of germline tumour cells following cisplatin treatment." (PMID 15655552, 2005). "This study showed that germline tumour cells not only exhibited lower EGFR expression but also were highly sensitive to DNA-damaging drugs, suggesting that the lack of EGFR expression contributes at least in part to the drug sensitivity of germline cells." (PMID 15655552, 2005). "For example, ZD6474 inhibits both VEGFR and EGFR tyrosine kinase activity, and therefore has the ability to block two key processes in tumour development." (PMID 15928655, 2005). "We compared the distribution of patients and tumor characteristics and treatment according to EGFR expression (staining intensity and extent) to assess the presence of potential imbalances in the known prognostic variables." (PMID 15967033, 2005). "Two promising targets are the vascular endothelial growth factor (VEGF) pathway, which is a key mediator of tumour angiogenesis, and the epidermal growth factor receptor (EGFR)." (PMID 15928653, 2005). "We also noted that EGFR protein was generally higher in cell lines than primary tumours despite comparable mRNA levels." (PMID 15956968, 2005). "The consequences of aberrant EGFR tyrosine kinase activity include increased tumour cell proliferation, survival and invasiveness, as well as the overexpression of proangiogenic factors such as VEGF." (PMID 15928657, 2005). "Gefitinib exerts antitumour activity through inhibition of EGFR-TK, but its antitumour activity cannot be predicted by EGFR expression in tumours." (PMID 15870831, 2005). "In fact, expression of EGFR is part of the definition of 'basal-like' tumours proposed by Nielsen and coworkers." (PMID 16280056, 2005). "Several antibodies have also been developed that specifically target the tumour-specific de2-7 EGFR." (PMID 15770208, 2005). "To support this, we have shown that tumour models that are known to be either sensitive (for example, A431 and LoVo) or insensitive (for example, PC-3 and Calu-6) to the selective EGFR tyrosine kinase inhibitor gefitinib, are all sensitive to ZD6474." (PMID 15928657, 2005). "Epidermal growth factor receptor (EGFR) is frequently amplified and/or mutated in a number of human tumours and abnormal signalling from this receptor is believed to contribute to the malignant phenotype seen in these tumours." (PMID 16189524, 2005). "Most tumours, as expected, contained elevated EGFR protein compared to normal kidney, although these levels were substantially lower than in RCC cell lines." (PMID 15956968, 2005).
tumor (continued). "Most of the tumours expressed more EGFR protein than the corresponding normal tissue, yet EGFR levels were up to 30-fold higher in cell lines despite comparable levels of mRNA." (PMID 15956968, 2005). "The pathological processes targeted include vascular endothelial growth factor-dependent tumour angiogenesis and epidermal growth factor receptor-dependent tumour cell proliferation and survival." (PMID 15928654, 2005). "Any inhibitory effect of ZD6474 in this tumour model can be considered to be a function of its anti-VEGFR activity, since tumour growth was unresponsive to a specific inhibitor of EGFR tyrosine kinase." (PMID 15928657, 2005). "Gefitinib is a small molecule inhibitor that specifically binds and inhibits the EGFR tyrosine kinase and has been shown to inhibit the growth, proliferation, survival and invasion of a range of tumour cells overexpressing EGFR." (PMID 16189524, 2005). "Our data demonstrate a new therapeutic effect of sequence specific suppression of EGFR gene expression by RNAi, enabling inhibition of tumor proliferation and growth." (PMID 15987532, 2005). "The overexpression of EGFR in many types of epithelial cancers EGFR renders it an attractive target for tumour-targeted antibody therapy." (PMID 15770208, 2005). "Introduction of a protein tyrosine kinase inhibitor selectively blocks proliferation of EGFR-expressing tumour cells, suggesting a role for EGFR in tumour cell growth." (PMID 15655552, 2005). "Epidermal growth factor receptor is necessary for cisplatin-mediated apoptosis in tumour cells, suggesting a possible involvement of EGFR pathway in mediating the repair of drug-induced DNA damage(s)." (PMID 15655552, 2005). "Increasing evidence has shown that the overexpression of EGFR closely correlates with advanced tumour stage and metastasis, and poor clinical outcome in many human cancers including breast, cervix, lung, bladder, and head and neck." (PMID 15785737, 2005). "To confirm the correlation of EGFR mutations with smoking, we conducted a detailed study of EGFR gene mutations in NSCLC patients who underwent tumour resection at a particular Japanese hospital." (PMID 16052218, 2005). "While most tumours overexpressed EGFR compared to matched normal controls, only two of 12 contained EGFR levels comparable to those observed in RCC cell lines." (PMID 15956968, 2005). "An immunohistochemical analysis indicated that most of the primary germline tumours we tested expressed very low level of EGFR." (PMID 15655552, 2005). "Overexpression of the epidermal growth factor receptor (EGFR) has been observed in many tumours including the breast, lung, colon, prostate, head and neck, and brain, and increased EGFR expression frequently correlates with more aggressive clinical course." (PMID 15770208, 2005). "Previous preclinical studies have relied on MAPK or Akt activity, representing preserved functional signals from EGFR activation, as a parameter of tumour response to gefitinib treatment." (PMID 15785737, 2005). "Cell count, colony assay, scratch assay, MTT assay in vitro and tumor growth assay in athymic nude mice in vivo were used to assess the functional effects of EGFR silencing on tumor cell growth and proliferation." (PMID 15987532, 2005). "By targeting these two pathways, ZD6474 has the potential to offer the combined benefits of directly inhibiting tumour cell proliferation and survival like other EGFR inhibitors, as well as inhibiting tumour angiogenesis by inhibiting VEGF activity." (PMID 15928653, 2005). "Intriguingly, EGFR/ERBB1 mRNA was significantly underexpressed in all of the four tumours analysed with increased LRIG1 copy number." (PMID 16168117, 2005). "Because the EGFR is overexpressed in many types of cancer, and its blockade often inhibits tumour growth, this receptor is a rational target for novel cancer therapeutics." (PMID 15770208, 2005).
tumor (continued). "Activation of the EGFR is involved in malignant transformation and tumour growth through the inhibition of apoptosis, cellular proliferation, promotion of angiogenesis, and metastasis." (PMID 15238978, 2004). "Relative expression (tumour/paired normal tissue ratio standardised for β-actin) was calculated for EGFR and c-erbB-2 mRNA." (PMID 15213712, 2004). "Immunohistochemical studies have reported EGFR overexpression in 22–81% of NSCLC tumours depending on the antibody used and cut point that defines overexpression." (PMID 15365565, 2004). "EGFR TKIs can sometimes produce remarkable and surprisingly rapid tumour shrinkage and they have the potential to alter tumour biology and the rate of tumour progression." (PMID 15150574, 2004). "Combining hPGFS with EGFR and other tumour markers will certainly increase the accuracy of molecular diagnosis for specific type of tumours." (PMID 14997212, 2004). "As monotherapy or combination therapy, EGFR-targeted agents have demonstrated promise in treatment of several tumour types." (PMID 14760365, 2004). "In contrast to the INTACT trial design, only patients with EGFR expressing tumours were enrolled in the study." (PMID 15238978, 2004). "Epidermal growth factor receptor is highly expressed in a number of human tumours, and many clinical trials of EGFR-targeted therapies have been going on." (PMID 15083186, 2004). "Blockade of the EGFR signalling pathways results in not only retardation of cell cycle progression but also induction of apoptosis in EGFR-expressing tumour cells." (PMID 14710235, 2004). "The signalling pathways downstream from the epidermal growth factor receptor (EGFR) play a key role in the control of tumour cell proliferation, angiogenesis and metastatic spread." (PMID 15545965, 2004). "In this respect, it has been reported that a combination of the EGFR-directed mAb C225 and the erbB2 directed mAb 4D5 or using dual EGFR/HER2 inhibitors inhibited proliferation of tumor cell lines more strongly than either mAb alone." (PMID 15305194, 2004). "EGF treatment of tumour cell lines induces HIF-1α expression and constitutively active mutations of EGFR potentiate hypoxic induction of other targets of HIF-1α such as VEGF." (PMID 15365565, 2004). "At the cellular level, EGFR inhibitors result in cell cycle arrest at the G1 phase, decrease tumour neovascularisation by downregulating expression of angiogenic mediators such as vascular endothelial growth factor (VEGF), and promote apoptosis." (PMID 15238978, 2004). "The overall frequency of elevated hPGFS expression in SCCHN tumours (40.5%) exceeds the frequency of EGFR (32.4%), a well-known molecular marker and drug target for multiple types of tumours." (PMID 14997212, 2004). "EGFR is expressed or highly expressed in a variety of human tumours including non-small-cell lung cancer (NSCLC), breast, bladder, ovarian and head and neck and is therefore a promising target for cancer therapy." (PMID 15560844, 2004). "Epidermal growth factor receptor is frequently overexpressed in NSCLC tumour cells, ranking from 65 to 84%." (PMID 15226769, 2004). "The adaptor protein PLC-γ1 was chosen as a target due to its pivotal role in the EGF-dependent migration and invasiveness of tumour cells mediated by EGFR and c-erbB-2 signalling." (PMID 14710234, 2004). "In Phase Ib clinical trials, a loading dose of 400 mg m−2 at week 1 followed by a weekly maintenance dose of 250 mg m−2 achieved almost complete saturation of EGFR in tumour tissue." (PMID 14760365, 2004). "Attempts have been made to identify tumour phenotypic and genotypic profiles that confer sensitivity to EGFR TKIs." (PMID 15150574, 2004). "We have found that 20.1 and 31.8% of cases were positive for EGFR and c-erbB-2, respectively, and 45 and 45.1% of tumours overexpressed for c-erbB-3 and c-erbB-4, respectively." (PMID 15480434, 2004).
tumor (continued). "Activation of the epidermal growth factor receptor (EGFR) triggers downstream signaling pathways that regulate many cellular processes involved in tumour survival and growth." (PMID 15560844, 2004). "A higher frequency of elevated hPGFS expression in SCCHN tumours, compared to the frequency of increased EGFR expression, was found in this study." (PMID 14997212, 2004). "We observed that the median expression levels of EGFR were higher in the control ALNs than in the tumour cell positive lymph nodes." (PMID 15083181, 2004). "EGFR signalling has been reported to be important for tumour cell proliferation, inhibition of apoptosis, angiogenesis, metastasis and sensitivity to chemotherapy and radiotherapy." (PMID 15150574, 2004). "Epidermal growth factor receptor signalling promotes angiogenesis, cell proliferation, tumour invasion and inhibits tumour suppressor gene activity and apoptotic signalling." (PMID 15365565, 2004). "Many studies have involved patients with tumours that widely express EGFR, including NSCLC, colorectal cancer, squamous-cell carcinoma of the head and neck (SCCHN) and breast cancer." (PMID 14760365, 2004). "Tumour expression of both genes correlated with OR (hAG2, P=0.0002; hAG-3, P=0.0012), and inversely correlated with epidermal growth factor receptor (EGFR) (P=0.003)." (PMID 12592373, 2003). "EGFR mediates signals that stimulate proliferation, migration and metastasis in many types of tumours, including RCC." (PMID 14520461, 2003). "Significant correlations were found between EGFR expression and tumour extent (T stage) (P=0.010), lymph node status (N stage) (P=0.019), clinical overall stage (P=0.002), tumour depth (P=0.035), and ECS of lymph node (P=0.025)." (PMID 12915878, 2003). "EGFR overexpression has been shown to be statistically associated with T stage, N stage, overall TMN stage, primary tumour depth, lymph node extra-capsular spread, and poor survival." (PMID 12915878, 2003). "In this study, using quantitative PCR and immunohistochemistry, it was shown that the expression of LRIG1 was decreased and the ratio of EGFR/LRIG1 was increased in tumours vs normal tissue." (PMID 14520461, 2003). "mRNA copy number per ng cDNA was correlated with ER status (+, positive: −negative), age (less than 50 years of age versus 50 years of age and over), EGFR status, and tumour grade (grades I and II vs grade III)." (PMID 12592373, 2003). "In our study of 134 RCCs, the cellular location of immunostaining was evaluated and patients with EGFR-positive tumours with prominent membranous staining had a good prognosis." (PMID 14520458, 2003). "The EGFR/LRIG1 ratio was increased at least 2.5-fold in all tumours matched with the corresponding kidney cortex." (PMID 14520461, 2003). "The increased EGFR/LRIG1 ratio found in RCC lends support to the suggestion that LRIG1 functions as a tumour suppressor and inhibitor of EGFR in humans." (PMID 14520461, 2003). "The observed downregulation of LRIG1 and increased EGFR/LRIG1 ratios are consistent with LRIG1 being a suppressor of oncogenesis in RCC by counteracting the tumour-promoting properties of EGFR." (PMID 14520461, 2003). "Gefitinib (4-(3-chloro-4-fluoroanilino)-7-methoxy-6-(3-morpholinopropoxy)quinazoline (ZD1839)), a specific EGFR-TK inhibitor, is currently in clinical testing for various tumour entities." (PMID 14583782, 2003). "An exploratory analysis of EGFR expression in tumour biopsies has recently been performed by immunohistochemistry in the IDEAL 1 and 2 trials, in which formalin-fixed, paraffin-embedded sections were stained with the 2-18C9 clone antibody." (PMID 14661046, 2003). "Immunohistochemistry, on the other hand, offers a simple and economical means for cellular detection of EGFR and analysing its location in tumour cells." (PMID 14520458, 2003).